CDK1 (cyclin dependent kinase 1)
Diseases named in the same sentence as CDK1 in open-access papers (continued):
Sharing a sentence is not in itself a finding about the gene and the disease.
tumor (continued). "CDK1 is involved in multiple oncogenic pathways, and inhibiting the expression and activation of CDK1 might exert an anti-tumor effect." (PMID 40040723, 2025). "Dinaciclib is a selective Cdk1/2/5/9 inhibitor with anti-tumor activity." (PMID 39668430, 2024). "In addition, some studies have shown that targeting CDK1 can reduce the efflux or metabolism of chemotherapy drugs by tumor cells, thereby increasing the accumulation and effect of chemotherapy drugs at the tumor site." (PMID 38638876, 2024). "In particular, CCNA2, CCNB2, CDK1, and TOP2A were found to be significantly upregulated in HBV‐positive HCC tumor samples and may serve as promising diagnostic biomarkers." (PMID 38895552, 2024). "Therefore, simultaneous inhibition of Pin1 and CDK1 elevated apoptosis, decreased proliferation, and impacted stemness of tumor cells to delay tumor growth." (PMID 38167292, 2024). "Research has shown that CDK1 is excessively expressed in tumor cells, such as HCC." (PMID 38895552, 2024). "Additionally, Western blot analysis of tumor tissue indicated that 50 mg/kg cyclobrachycoumarin decreased the expressions of CDK1, total PARP, and survivin while enhancing cleaved PARP levels in vivo." (PMID 39683841, 2024). "Cyclin-dependent kinase 1 (CDK1) was inhibited by the neo-synthetic bis(indolyl)thiazole analogue of 7, which, when overexpressed, may promote uncontrolled tumor cell proliferation." (PMID 38535455, 2024). "Furthermore, when we knocked down CDK1, we observed a partial restriction in the tumor growth that had been enhanced by elevating HADHA expression." (PMID 37986001, 2023). "The CDK1/stroma and CDK1/tumor clusters both had varying degrees of intercellular communication with other cell types in the communication network, especially tumor cells and macrophages." (PMID 36950551, 2023). "Besides these, other downstream oncoprotein substrates of CDK1 participate in multiple signaling pathways mediating tumor progression." (PMID 37311884, 2023). "In addition, the SPP1-CD44 pair was significantly activated in the interactions between the CDK1/stroma cluster cells and other cell types, especially macrophages, CDK1/tumor cluster cells, and mast cells." (PMID 36950551, 2023). "Silencing CDK1 impaired tumor stemness and reduced a subset of CSCs." (PMID 37743465, 2023). "Suppression of CDK1 by fisetin reduced tumor stemness and phosphorylation of CDK1 and STAT3." (PMID 37743465, 2023). "In addition, we verified the important role of CDK1 in cell proliferation and found that cells with high CDK1 expression interacted with multiple signaling pathways to reshape the tumor immune microenvironment." (PMID 36950551, 2023). "EGFR-modified bacterial minicells loaded with siRNA could validly knock down the expression of PLK1, KSP, CDK1, and have the excellent ability to suppress tumor cell proliferation in HCT116 tumor-bearing mice." (PMID 37896250, 2023). "Out of the 55 upregulated genes, a 5 gene-signature (CDK1, EZH2, CCNB1, CCNA2, and AURKA) involved in cell regeneration was positively correlated with the status of tumor hypoxia and clustered with stemness-associated genes, as recognized by Parametric Gene Set Enrichment Analysis (PGSEA)." (PMID 37189841, 2023). "CCNB1 and CDK1 are key cell cycle molecules that can affect tumor growth and metastasis." (PMID 37994323, 2023). "The present findings indicate that CDK1 might have a critical role in tumor stemness through its kinase function to catalyze the transfer of phosphate groups from ATP to target proteins." (PMID 37743465, 2023). "The selective inhibition of CDK1 by small-molecule inhibitors, purvalanol or roscovitine, causes the suppression of the apoptosis protein BIRC5 (survivin), which is essential for the survival of MYC-driven tumor cells." (PMID 37443779, 2023). "Cell cycle arrest and CDK1 regulation play important roles in the apoptosis of tumour cells." (PMID 37658940, 2023).
tumor (continued). "Cyclin-dependent kinase 1 (CDK1) plays an important role in tumor initiation in other tumors, but the function of CDK1 in PDAC remains unclear." (PMID 37743465, 2023). "CDK1 plays an essential role in reshaping the tumor immune microenvironment and might be a prognostic and treatment biomarker in LUAD." (PMID 36950551, 2023). "Treatment with siODF2L-LNPs successfully decreased ODF2L expression in ID8 tumors but not in the main organs, including the heart, liver, spleen, lung, and liver, resulting in both the substantial activation of CDK1 and exacerbation of DNA damage in the tumor cells when combined with AZD1775." (PMID 36378528, 2023). "Interestingly, both the incoming and outgoing patterns of CDK1/tumor cells were similar to those of tumor and epithelial cells." (PMID 36950551, 2023). "In addition, we showed that CDK1/PBK/CHEK1 overexpression promotes GBM tumor aggressiveness, immunosuppression, and progression by recruiting the tumor-promoting immune cells such as the T Cells CD4+ Th2 subtype, MDSCs, and the TAM-M2 subtype." (PMID 38003585, 2023). "Based on the results of our study, CDK1/tumor cluster cells may release MDK to promote the proliferation of tumor cells and mediate the exhaustion of immune cells in an autocrine or paracrine manner." (PMID 36950551, 2023). "Previous studies revealed that CDK1 which could induce tumor proliferation was also positively correlated with CD4+ T-cells and CD8+ T-cells in HCC." (PMID 37313428, 2023). "The results showed that knockdown of CDK1 obviously suppressed tumor growth in this mouse model." (PMID 37743465, 2023). "CDK1 stabilizes HIF1A through direct phosphorylation of Ser668 to promote tumor growth." (PMID 37311884, 2023). "However, we found that the MDK-NCL pair was specifically activated in the interactions between the CDK1/tumor cluster cells and other cell types, especially tumor cells, fibroblasts, and CDK1/stroma cluster cells." (PMID 36950551, 2023). "We investigated the alterations of the CDK1 gene in different tumor samples from the TCGA cohort." (PMID 36090896, 2022). "In addition, there was a significant positive correlation between these top five genes and CDK1 in all tumor types from the TCGA database." (PMID 35681641, 2022). "Taken together, these data suggest that CDK1 is highly related to tumorigenesis and could be a potential target for tumor diagnosis and treatment." (PMID 35681641, 2022). "Up- or downregulating the expression level of RNA methylation regulatory proteins by targeting CDK1 may become a new approach for tumor prevention and treatment." (PMID 36090896, 2022). "Indeed, the present study showed that CCNA2, CEP55, KIF11, KIF4A, and ZWINT were the top five genes that were significantly and positively correlated with CDK1 in all tumor types from the TCGA database." (PMID 35681641, 2022). "Also, it has been shown that the use of CDK1 inhibitors can interfere with the proliferation of gastrointestinal mesenchymal tumor cells with high CDK1 expression." (PMID 36090896, 2022). "After adjusting tumor stage and radical resection, the multivariate Cox regression model of TCGA cohort suggested that high expression of CDK1 (adjusted HR = 1.541; adjusted P = 0.028) and CDK4 (adjusted HR = 1.721; adjusted P = 0.005) were statistically related to OS." (PMID 35193513, 2022). "Meanwhile, CDK1 expression in normal tissues was significantly lower than that in tumor tissues." (PMID 36078096, 2022). "CDK1 depletion promote cell-cycle arrest and ultimately inhibit tumor cell proliferation." (PMID 35651787, 2022). "Moreover, in animal models of pancreatic cancer, reduction of phosphorylation of CDK1, 2, 7, and 9 by AT7519 has been associated with reduction of tumor growth." (PMID 36266723, 2022).
tumor (continued). "As for the mechanism, it was demonstrated that NLE1 may execute its tumor-regulating function through activating E2F1-mediated transcription of CDK1, and PI3K/Akt signaling pathway was also supposed as a downstream of NLE1 in the regulation of NSCLC." (PMID 36818671, 2022). "Based on all or most of the algorithms, we observed a negative correlation between CDK1 expression and the infiltration values of tumor-associated fibroblasts in COAD, BRCA-Basal, THYM, HNSC, HNSC (human papillomavirus [HPV+]), LUSC, PRAD, and STAD tumors." (PMID 36090896, 2022). "In the GO enrichment analysis category of “molecular function,” the role of CDK1 in tumor pathogenesis might be related to protein binding, protein kinase binding, and ATP binding." (PMID 36090896, 2022). "The increased Cdk1 activation, in turn, facilitates the progression of tumor cells into mitosis." (PMID 35392228, 2022). "Acacetin shows a strong G1 and/or G2/M blockade effect, reduces the levels of CDK2, 4, and 6 in tumor cells in a dose-dependent and time-dependent manner, increases the level of p21, reduces the levels of cdc25c, CDK1, and cyclin B 1 protein, and makes cells stagnate in the G1 and G2/M phases." (PMID 36003621, 2022). "Additionally, significant promotion of the cell cycle was found in the hot tumor subgroup, as indicated by the higher expression of the important regulatory proteins Cyclin B1 and cyclin-dependent kinase 1 (CDK1), responsible for G2/M-phase progression." (PMID 36139700, 2022). "Related studies show that tumor suppressor genes can be suppressed by hypermethylation and oncogenes can be activated by hypomethylation, the differential expression of CDK1 phosphorylation in different TCGA tumors leads to genomic instability and accelerated tumor progression." (PMID 36090896, 2022). "This crucial role of CDK1 in inducing apoptosis helps to explain several studies reporting an association between absence of CDK1 expression in tumour tissue and decreased survival rates of patients." (PMID 34503199, 2021). "NSUN2-induced m5C in CDK1 mRNA promotes CDK1 translation, leading to tumor cell proliferation." (PMID 33922187, 2021). "However, CDK1 was also demonstrated to be involved in apoptin-induced apoptosis in HCC; this tumor-suppressing role of CDK1 is inconsistent with previous findings." (PMID 34844614, 2021). "CDK1/cyclin B1 complex formation has been demonstrated to mediate mitochondrial activity during cell cycle progression and stress responses, as well as to reprogram energy metabolism in adaptive tumor resistance." (PMID 34844614, 2021). "Finally, we demonstrated that CDK1 activity was maintained throughout the cell cycle, and that CDK1 inhibitors restored androgen sensitivity in CRPC tumor cells." (PMID 33932081, 2021). "In addition, targeting of CDK1 has shown potential for combination therapy with both ionizing radiation treatment and conventional chemotherapy, through sensitizing tumor cells and reducing resistance to these treatments." (PMID 34503199, 2021). "It has been reported that treatment with a CDK1 inhibitor could decrease tumor growth of HB and prolong the survival rate in an HB murine model." (PMID 33868991, 2021).
tumor (continued). "Proteins that contribute most strongly to proteotype-based classification include inositol polyphosphate-4-phosphatase, type II (INPP4B), cyclin-dependent kinase 1 (CDK1), and receptor tyrosine kinase 2 (ERBB2) are associated with estrogen receptor (ER) status, HER2 status tumor, and grade status." (PMID 34948142, 2021). "Researchers have demonstrated that CDK1 inactivation influences multiple tumors cell cycle progression, thereby CDK1 might be a tumor therapeutic target." (PMID 33686019, 2021). "Moreover, the addition of RO-3306, an inhibitor of CDK1, significantly inhibited tumor growth and enhanced enzalutamide sensitivity, providing a potential therapeutic target for clinical treatments." (PMID 33994848, 2021). "CDK1 is involved in cell proliferation and is a predictive tumor marker." (PMID 34484348, 2021). "Similarly, in nude mice, we confirmed that AKT/Wee1/CDK1 axis was also involved in tumor growth during exposure to high iodine." (PMID 33796458, 2021). "Up-regulation of CCNB2 and CDK1 accelerates tumor cell mitotic progression." (PMID 34944787, 2021). "Moreover, CDK1 knockdown decreased the phosphorylation, transcription activity, and nuclear distribution of SOX2, while knockout of SOX2 significantly reduced CDK1 overexpression-induced tumor-initiating capacity." (PMID 34621737, 2021). "Although the related research of CDK1 is mainly driven by the exploration of cell cycle regulation, a large number of studies in recent years have shown that CDK1 has a high diversity of functions, especially the important role in the survival of tumor cells." (PMID 34499615, 2021). "The cytoplasmic CDK1 expression increased as tumor grade progressed (p <0.001)." (PMID 33758599, 2021). "For example, miRNA‐490‐3p,43 miR‐31,44 and miR‐18645 could inhibit tumor progression by degrading CDK1 mRNA by targeting its 3′ UTR." (PMID 33259133, 2021). "Combined blockage of BCL-XL and CDK1/2/4 interfered with tumour growth in vivo." (PMID 34646365, 2021). "CDK1 is a regulator of cell cycle, whose activation inhibits anti-tumor immune response." (PMID 35047498, 2021). "CDK1 is known to play an essential role in the management of the cell cycle and tumor development." (PMID 33994848, 2021). "Moreover, Sox2 is related to tumour initiation, therefore an excessive expression of CDK1 promotes the development of CSCs in the tumour microenvironment by Sox2 activity." (PMID 34503199, 2021). "Taken together, these findings illustrate that CDK1 inhibition might specifically suppress the proliferative capacity of tumor cells." (PMID 33718368, 2021). "Meanwhile, CDK1 is an important antitumor target for inhibitor development in recent years, so it is very important to understand the regulation mechanisms of CDK1 expression for tumor therapy." (PMID 33259133, 2021). "CDK1 can regulate the cell cycle progression, apoptosis, and carcinogenesis of tumor cells." (PMID 33190424, 2021). "Regarding cell cycle markers, SNHG4 silencing increased, whereas miR-590-3p inhibition decreased, the protein levels of CDK1, cyclinB1, and cyclinA2 in the tumor samples; the effects of SNHG4 silencing on cell cycle markers were also significantly reversed by miR-590-3p inhibition." (PMID 33744866, 2021). "In addition, CCNE1, CCNE2, CCNB2, CCNA2, and CDK1 genes were highly expressed in fetal tumor tissues." (PMID 34395530, 2021). "CDK1 has been shown to promote tumor angiogenesis by stabilizing HIF-1α, and its disruption could inhibit retinal angiogenesis by inducing cell cycle arrest and apoptosis." (PMID 33393628, 2021). "Cell cycle-dependent protein kinase 1 (CDK1), which belongs to the serine/threonine-protein kinase family, is mainly active in the late G2 and early M phases, and high expression of active CDK1 can promote the G2/M transition and accelerate the growth of tumor cells." (PMID 33608020, 2021).
tumor (continued). "Interestingly, CDK1 expression of tumor tissues in protein levers further showed that the tumor volume and weight indeed correlated with CDK1 expression." (PMID 33145401, 2020). "Proteins encoded by CDK1, BUB1 and AURKB belong to the serine/threonine kinases family, and overexpression of them has been detected involved in various tumors prognosis via regulating tumor cell cycle." (PMID 32411535, 2020). "The restoration of c-Myc rescued the expression of CDK1 and Cyclin B1 in tumor samples." (PMID 33330479, 2020). "Overexpression of CDC25C may be related to the activation of the cyclin B1/CDK1 complex and promote the growth of the corresponding tumor, and there is a correlation between survival and proliferation rate." (PMID 32518522, 2020). "Therefore, it was proved that the loss of LMNA gene expression resulted in the up‐regulation of P16 and down‐regulation of CDK1, suggesting that the loss of the LMNA gene caused the proliferation and cell cycle arrest of the tumour cells." (PMID 32896989, 2020). "Decreased levels of CDK1 reduced tumor growth activity, and increased levels of CDK1 promoted PCa cells to develop in the direction of G2/M, which may be the cause of everolimus resistance." (PMID 33178832, 2020). "Consistently, Western blot assay showed that the expression of CDK1 and Cyclin B1 was restored in the c-Myc overexpression tumor sample accompanied by G9a and c-Myc protein expression level returning; meanwhile, autophagy was decreased after overexpression of c-Myc in the tumor sample." (PMID 33330479, 2020). "Cyclin-dependent kinase 1 (CDK1) is a mitotic kinase, it mainly mediates tumor-related cell cycle defects, misregulated CDK1 may cause tumor cell proliferation and genome instability." (PMID 33391348, 2020). "However, no significantly different survival times were observed between patients with high CDK1 expression levels and patients with low CDK1 expression levels at tumor stage 1 (log-rank P = 0.077)." (PMID 31886163, 2019). "CDK1 inhibition is selectively lethal in MYC-dependent human breast cancer cells." (PMID 30931929, 2019). "Furthermore, PVT1 downregulates miR-31 to enhance the expression of cyclin-dependent kinases 1 (CDK1) and facilitates tumor cell proliferation, migration, and invasion." (PMID 31380270, 2019). "Moreover, the protein levels of phosphorylated CDK1 in primary tumour tissues obtained from the mice were significantly increased after treatment by shikonin compared with that of the control group, especially for the 5 and 10 mg/kg groups." (PMID 30616572, 2019). "In the present study, the cdk1-cyclin B- and the cdk2-cyclin A-complex were reduced in parental cells treated with temsirolimus, whereas a strong up-regulation was seen in drug resistant tumor cells, particularly when re-treated with temsirolimus." (PMID 31167517, 2019). "Emerging studies suggest that selective targeting of CDK1 might constitute a novel plausible strategy for tumor treatment in certain contexts." (PMID 30931929, 2019). "Notably, Bim and CDK1 mediate complementary aspects of tumour cell suppression, namely cell death and proliferation, respectively." (PMID 31827192, 2019). "Our previous studies demonstrated that the C-terminal acidic domain (CAD) of TSPX is critical for its tumor suppressor functions, such as suppression of cyclin B/CDK1 phosphorylation activities, degradation of a HBV viral oncoprotein HBx, and inhibition of the androgen receptor (AR) transactivation." (PMID 30863497, 2019). "In addition, survival curves for HCC patients with different tumor stages were also plotted, which showed that the high CDK1 predicts poor overall survival in patients with tumor stage 2 (log-rank P = 0.0016) and tumor stage 3 (log-rank P = 0.013)." (PMID 31886163, 2019). "In HCC, the aberrant CDK1 expression could regulate the apoptin-induced apoptosis with a pivotal role in tumor progression." (PMID 31886163, 2019).